NLRP3 (NLR family pyrin domain containing 3)
Diseases named in the same sentence as NLRP3 in open-access papers (continued):
Sharing a sentence is not in itself a finding about the gene and the disease.
infection (continued). "Taken together, these results show that NLRP3 inflammasome-mediated IL-1β activation requires SVA infection, SVA genomic RNA, and protein synthesis." (PMID 35254168, 2022). "Compared to non-infection, the diffused infiltrations of Iba1+ macrophages induced by SARS-CoV-2 infection into the alveolar cavities were reduced by Nlrp3 deficiency." (PMID 34979342, 2022). "In summary, these data indicate that NLRP3 knockout can help to reduce the infection rate and effectively alleviate lung damage in mice exposed to A. fumigatus after radiation." (PMID 35761358, 2022). "A recent study showed that AIM2 can amplify signals of infection and trigger atypical NLRP3 activation, and another study showed that the inflammasome adaptor ASC is required for their assembly." (PMID 36151570, 2022). "In the priming step, expressions of NLRP3, pro-IL-1β, and pro-IL-18 are increased in response to stimuli, such as infection, injury, and ROS." (PMID 36289519, 2022). "We observed a 4 to 5 mBU dip over the period of infection, confirming IAV infection caused a conformational change in NLRP3." (PMID 35062292, 2022). "It is also likely that OXSR1 interacts with intracellular infections independently of NLRP3 inflammasome, potentially through the direct control of intracellular and vacuolar ion concentrations." (PMID 35545295, 2022). "We now know that Mtb is able to inhibit the AIM2- and NLRP3-inflammasome during ex vivo infections but is there a role for the inflammasome for increasing host resistance or susceptibility during in vivo Mtb infections?" (PMID 35237260, 2022). "The only known report of inflammasome activation by Hantaan virus, a negative-sense RNA virus in the hantaviridae family, found activation of the NLRP3 inflammasome along with secretion of IL-1β upon infection of THP-1 cells." (PMID 36298668, 2022). "In contrast, later during infection, NLRP3 activation and production of IL-1β contributes to the induction of the cytokine storm and severe immunopathology." (PMID 36580480, 2022). "Chemical inhibition of NLRP3 in vivo revealed that early in infection, NLRP3 inflammasome activation is protective and indispensable to control IAV replication and lung pathology." (PMID 36580480, 2022). "NOD-, LRR-, and pyrin domain-containing 3 (NLRP3) is a cytosolic innate immune sensor of cellular stress signals, triggered by infection and sterile inflammation." (PMID 36127465, 2022). "At different times (15, 30, 45 and 60 min) after infection, the protein levels of MyD88 and NLRP3 and the phosphorylation of Iκbα and p65 were significantly upregulated compared with those at 0 min (P < 0.01)." (PMID 35578336, 2022). "Many studies have confirmed that NLRP3 inflammasome, which is a widely studied inflammasome, is related to infection, tumor, autoimmune diseases." (PMID 36418383, 2022). "Infection with siNLRP3 resulted in a decrease in NLRP3 expression, as determined by Western blotting." (PMID 35915511, 2022). "NLRP3 is normally maintained in an autoinhibited state, however, it is activated upon sensing diverse stress signals and signatures of infection, leading to the assembly of the NLRP3 inflammasome, which can elicit both inflammatory and antiviral responses." (PMID 36110852, 2022). "After 48 h post-infection, the mRNA expressions of NLRP3 and GSDMD were higher in the RHwx2−/− group compared with the RH and RHwx2+/+ groups, and the difference was statistically significant (P < 0.05)." (PMID 36471417, 2022). "The biological relevance of the neutrophilic NLRP3 inflammasome has been evaluated in various conditions, including sterile inflammation and infections conferring to this pathway, either protective or deleterious phenotypes." (PMID 35406754, 2022). "Consistent with previous studies, we found an induction of NLRP3 and Caspase-11 inflammasome components early in the infection." (PMID 36318583, 2022).
infection (continued). "As an essential component of the innate immune system, the NLRP3 inflammasome is important for antiviral host defense, and its abnormal activation can lead to pathological tissue damage during infection." (PMID 36034710, 2022). "Young mice intraperitoneally treated with MCC950 three days post IAV virus infection showed reduced NLRP3 and activated caspase-1, regained weight 8-9 days post-infection and improved survival compared to their PBS-treated IAV-infected counterparts." (PMID 36110852, 2022). "During pathogen infection, ZBP1 can be essential for activation of NLRP3, possibly recruiting NLRP3 after polyubiquitination during infection." (PMID 35626718, 2022). "Aberrant NLRP3 are involved in various inflammatory conditions, infection immune responses, and tumorigenesis including lung cancer." (PMID 36323738, 2022). "ST SPI-II has been shown to induce NLRP3 activation, and NLRP3 ablation significantly protected against ST-induced IL-1β release upon infection." (PMID 34864057, 2022). "Despite its importance in infections and sterile tissue damage, the exact mechanisms controlling and enabling NLRP3 activation are still being elucidated." (PMID 36127465, 2022). "Nucleotide-binding oligomerization domain (NOD)-like receptor pyrin domain-containing protein 3 (NLRP3) is a key inflammasome sensor of cellular stress and infection that is involved in the innate immune system." (PMID 36699095, 2022). "On Day 7 post-infection with E. tenella, the levels of the components of the ChTLR15/NLRP3/IL-1β pathway in the caeca were again quantified, and the anticoccidial effects were assessed." (PMID 35303923, 2022). "In this study, on Day-2 after irradiation, the rate of infection with A. fumigatus conidia was highest, and the expression levels of proteins related to NLRP3-mediated pyroptosis were high." (PMID 35761358, 2022). "In mouse models, IL-9 not only exerts inflammation by promoting this NLRP3 inflammasome during the initial stages of VVC but also increases tolerance against infection toward the recovery phase by inducing the IL-1 receptor antagonist." (PMID 36159646, 2022). "In infections with influenza A virus, however, activation of NLRP3-dependent inflammasome complex contributes to protective responses and to ameliorate illness." (PMID 36189282, 2022). "The NLRP3 inflammasome plays protective role against the infections of EV71 and coxsackievirus B3 (CVB3) that is another member of EV-B, as evidenced by that the higher viral load and severe symptoms were observed in the NLRP3 inflammasome-deficient mice." (PMID 36026486, 2022). "Collectively, the data show that the activated NF-κB signaling and NLRP3 inflammasome induced by ASFV-H240R infection exhibit the antiviral effect." (PMID 36326277, 2022). "These mutant mitochondria are susceptible to infectious agents and are further compromised during infection, resulting in a dysfunctional state including exaggerated activation of NLRP3 inflammasomes and release of proinflammatory cytokines." (PMID 36300112, 2022). "The NLRP3 inflammasome is triggered by a variety of situations of host ‘danger’, including infection." (PMID 36290721, 2022). "Activation of GBPs also contributes to IL-1β and IL-18 processing and secretion during infection, and induces pyroptosis through activating the NLRP3 inflammasome and promoting LPS release into the host cells cytosol." (PMID 36248872, 2022). "The NLRP3 inflammasome mediates activation of caspase-1 and secretion of IL-1β in response to infection and cellular damage." (PMID 35720309, 2022). "Based on P. gingivalis and other similar pathogens infection, this chapter summarized the complex interaction through the NLRP3 inflammasome pathway and cGAMP-cGAS-STING signaling pathway." (PMID 35846745, 2022). "In the case of L. interrogans, our group published that NLRP3 is activated upon infection of murine macrophages." (PMID 35937697, 2022).
infection (continued). "The NLRP3 inflammasome is highly activated in response to S. aureus and plays conflicting roles with regard to infection." (PMID 35626718, 2022). "The activation of NLRP3 inflammasome and pyroptosis is an important part of innate immune response during the infections of EVs." (PMID 36026486, 2022). "Recently, it was found that NLR family pyrin domain containing 3 (NLRP3) inflammasome is strongly involved in lung inflammation and infection in humans and rodents." (PMID 35777914, 2022). "The infection promoted the secretion of mature IL-1β through activation of NLRP3 inflammasomes and downstream caspase-1." (PMID 35846745, 2022). "Here, we demonstrate that the activation of the NF-κB signaling and NLRP3 inflammasome was markedly induced in PAMs upon ASFV-ΔH240R infection compared with ASFV-WT." (PMID 36326277, 2022). "Additional experiments indicated that the low-level inflammasome signaling in macrophages following infection by ST-ΔfliF was dependent on NLRP3." (PMID 34864057, 2022). "Gp78 siRNA infection greatly inhibited the increase of NLRP3 ubiquitination in CUMS mice resulted from acacetin treatment, leading to the enhancement of NLRP3 and Cleaved-Caspase1 expression as well as the reduction of neurons and goblet cells." (PMID 36299901, 2022). "A reduced activity of the neutrophilic NLRP3 inflammasome during infection was also illustrated in vitro in response to the protozoan Toxoplasma gondii infection." (PMID 35406754, 2022). "Metabolic activity and redox state are all intricately linked to each other and connect mitochondrial network dynamics during infection and NLRP3 inflammasome activity." (PMID 34638790, 2021). "On day 30, the NLRP3 level of the infection group (0.50 ± 0.05) (P = 0.004) was still higher than that of the HC group, while the level returned to almost normal in the laser group (0.39 ± 0.04) (P = 0.337)." (PMID 34908455, 2021). "To this end, our RT-PCR results were in agreement with the microarray data and we observed differential expression of caspase-1, caspase-4, and caspase-8 and NLRP3 in MDR-PA induced infection." (PMID 35046947, 2021). "Researchers also observed NLRP3 inflammasome activation induced by E. coli, C. rodentium and Staphylococcus aureus infection in macrophages." (PMID 34594329, 2021). "Mtb activated the canonical NLRP3 inflammasome by inducing potassium efflux upon the infection of monocytes and macrophages, followed by the GSDMD-dependent pyroptosis." (PMID 34163438, 2021). "As an important component of innate immune system, the NLR family pyrin domain-containing 3 (NLRP3) inflammasome plays a critical role in defense against pathogen infection." (PMID 34603335, 2021). "WT and Mt3-/- mice were treated i.p. with MCC950 (NLRP3 inhibitor) followed by infection i.p. with E. coli." (PMID 34867993, 2021). "Pairwise analysis of transcripts from C57BL/6 wild-type and Nlrp3−/− mice on days 3 and 7 post-infection was performed to determine differentially expressed genes between these strains of mice." (PMID 34690967, 2021). "The NACHT, leucine-rich repeat (LRR), and pyrin domain (PYD)-containing protein 3 (NLRP3) inflammasome is a protein complex that functions as a platform for rapid induction of the inflammatory response to infection or sterile injury." (PMID 33673188, 2021). "In order to confirm the NLRP3 protein expression levels, Western blotting assays were conducted to detect the expression of NLRP3 protein at different infection doses (MOI = 0.1, 0.5, and 1)." (PMID 34869071, 2021). "Assuming that activation of the NLRP3 inflammasome is an upstream event, which also triggers mitochondrial damage, treatment with the NLRP3 inhibitor MCC950 should prevent a change in the ΔΨm upon infection." (PMID 34718331, 2021). "In regulating microbe-elicited ROS production during an antimicrobial response, many studies showed that host PRRs (mainly TLR2, TLR4, NOD2, NLRX1, and NLRP3) and redox modulation alleviated pathogen infection." (PMID 34299310, 2021).
infection (continued). "In this study, inflammasome pathway analysis showed that infection with virulent strains of T. cruzi leads to high increase in the expression of NLRP3, caspase-1 and IL-1β in the myocardium." (PMID 34336720, 2021). "IL-1β is a proinflammatory cytokine in the toll-like receptor signaling and NLRP3 inflammasome pathways, which are crucial for host defense responses to infection." (PMID 33469074, 2021). "Because GT pathology occurred late post infection, we propose early high infection loads trigger NLRP3-dependent innate immune programming which is important for the development of late pathology." (PMID 34526512, 2021). "One of the critical features of the NLRP3 inflammasome is the ability to sense a wide array of danger signals derived from infection, the environment, and the host itself." (PMID 33534121, 2021). "A similar trend was also observed for pERK1/2, with significantly elevated levels being observed at 2 and 3h post-infection in the Nlrp3−/− compared to the F. tularensis LVS-infected wild-type macrophages." (PMID 34690967, 2021). "Many reports have documented that infection with MTB triggers NLRP3 inflammasome activation in vitro." (PMID 33503864, 2021). "Salmon analysis followed by Wald Test to establish the statistical significance (q<0.05) revealed that seven genes were upregulated in wild-type mice on day 3 post-infection, compared to Nlrp3−/− mice." (PMID 34690967, 2021). "The grayscale analysis results showed that the protein expression levels of NLRP3 were significantly upregulated in a dose-dependent manner along with the increased infection dose of V. alginolyticus (**p < 0.01 or ***p < 0.001)." (PMID 34869071, 2021). "NLRP3 inflammasome activation impaired agonist- or infection-induced TLR signaling and cytokine production through the proteolytic cleavage of MyD88 by caspase-1." (PMID 35069570, 2021). "Infection by different RNA viruses can lead to NLRP3 inflammasome activation, which favors the host by aiding in viral clearance." (PMID 34952919, 2021). "The NLRP3 inflammasome drives inflammation in response to tissue damage and infection by promoting the processing and release of IL‐1β." (PMID 33145969, 2021). "The inflammasomes, and more specifically the NLRP3 inflammasome, a crucial component of the innate immune system, is usually activated in response to infection or tissue damage." (PMID 33776778, 2021). "This leads to a higher level of expression of NLRP3, inflammasome activation and release of IL-1β and IL-18 pro-inflammatory cytokines in response to infection." (PMID 34829842, 2021). "This review summarizes the current literature on the role of the NLRP3 inflammasome in the pathogenesis of AD, and its involvement in infections, particularly SARS-CoV-2." (PMID 34209586, 2021). "This was a paradoxical finding as it was inconsistent with an infection-dependent stimulus that was driving the activation of the NLRP3 inflammasome in infiltrating macrophages." (PMID 34526512, 2021). "In summary, our results demonstrate that NLRP3 inhibited autophagy by binding to mTOR, while QFY reversed infection-impaired autophagy through down-regulation of NLRP3." (PMID 35111047, 2021). "On day 7 post-infection, 42 genes were significantly upregulated in the wild-type mice, while 12 genes were found to be upregulated in the Nlrp3−/− mice." (PMID 34690967, 2021). "Previously, another study demonstrated HSV-1 infection induces the activation of the NLRP3 inflammasomes early during in vitro infection of fibroblasts." (PMID 34638790, 2021). "Western blotting combined with relative gray value analysis data showed that the protein expression levels of NLRP3 were significantly upregulated in a time-dependent manner during the monitored infection time of V. alginolyticus (*p < 0.05 or **p < 0.01)." (PMID 34869071, 2021). "infection in bMECs induced an inflammatory response through the NF-κB and NLRP3 inflammasome pathways." (PMID 34895324, 2021).
infection (continued). "Targeting NLRP3 to supress IL-1β production means IL-1β can still be produced by other pathways if the body encounters an acute infection." (PMID 34439904, 2021). "Very recently, NLRP3 activation was confirmed in platelets upon infection with dengue virus, and the involvement of the envelope protein domain III has been evidenced as an important inducer of platelet pyroptosis related to NLRP3 activation." (PMID 34360659, 2021). "The activation of NLRP3 inflammasome by microbial stimuli plays a critical role in regulating IL-1β and IL-18 secretion during infection." (PMID 34564598, 2021). "During mice infections, both NLRP3 and Pak1 chemical inhibition or gene knock-out prevented CNF1-induced bacterial clearance during bacteremia." (PMID 33914853, 2021). "At all time point post-infection, the positive cell rate of NLRP3 and caspase-1 in the HPI infection groups were significantly higher than those in the control group (P < 0.01)." (PMID 33678162, 2021). "In the context of infection, B. abortus induces ER stress and subsequently NLRP3 inflammasome activation." (PMID 34201509, 2021). "Of several inflammasome complexes known to activate caspase-1, the most commonly evaluated is the NLRP3 inflammasome, which is a multiprotein platform that is activated upon cellular stress or infection." (PMID 33839695, 2021). "Paradoxically, NLRP3 inflammasome activation in macrophages occurred independently of macrophage infection." (PMID 34526512, 2021). "Infection with mCoV-A59 further enhanced caspase-1 cleavage (p20 active heterodimer) as well as expression of inflammasome components, Casp1 and Nlrp3, in old mice." (PMID 34151773, 2021). "In THP-1 cells, NAIP/NLRC4 and NLRP3 played redundant roles in inflammasome activation during infection with S. Typhimurium." (PMID 33380493, 2021). "In our study, we observed that inhibition or knockdown of NLRP3 markedly blocked H2-induced Casp1 activation and mature IL-1β secretion and also had a significant effect on cell death, indicating that H2 infection activated the NLRP3 inflammasome pathway." (PMID 34009097, 2021). "The transcript levels of DNA sensors Aim2, cGas, and Sting were also significantly elevated in the Nlrp3−/− mice on day 7 post-infection than those observed for F. tularensis LVS-infected wild-type mice." (PMID 34690967, 2021). "Nlrp3−/− mice also had significantly higher anti-inflammatory cytokine IL-10 in the lungs, especially on day 3 post-infection." (PMID 34690967, 2021). "The transcripts of Tlr1, Tlr5, Tlr11, and Nod2, Nlrp1a, Naip2, and Nlrc4 were significantly higher in the Nlrp3−/− than wild-type mice on day 7 post-infection." (PMID 34690967, 2021). "The NLRP3 inflammasome is related to the innate immune recognition of S. schenckii to exert an adaptive immune response for protection against infection." (PMID 34071562, 2021). "Collectively, these results demonstrate that at all infection doses of F. tularensis LVS tested, the Nlrp3−/− mice survived better than the wild-type mice, further cementing the notion that Nlrp3 enhances the susceptibility to F. tularensis infection." (PMID 34690967, 2021). "In human and murine macrophages, NAIP/NLRC4 and NLRP3 are triggered to form inflammasomes upon infection with S. Typhimurium." (PMID 33380493, 2021). "The wild type and NLRP3 KO THP-1 cells were infected with SFTSV (MOI = 1) or stimulated with LPS/Nigericin or mock infection." (PMID 33708197, 2021). "In SFTSV infected cells, accumulation of NLRP3, pro-caspase-1, and cleaved caspase-1 was observed compared with the mock infection, and ASC dimer, trimer, and oligomer were detected in the infected cells." (PMID 33708197, 2021). "Nevertheless, these results demonstrate the importance of mitochondrial dynamics in NLRP3 inflammasome assembly and activation, a crucial function of macrophages during infection." (PMID 34337844, 2021).